IL33 (interleukin 33)
Diseases named in the same sentence as IL33 in open-access papers (continued):
Sharing a sentence is not in itself a finding about the gene and the disease.
hookworm infection (4 papers, 2013 to 2024). "In collaboration with the Herbert group, we showed that macrophages and inflammatory DCs were implicated in Th2 responses following hookworm infection and that DC-derived IL-33 was sufficient to support Th2 skewing in vitro." (PMID 31940364, 2020). "We have previously shown critical roles for TFF2, TFF3 and the alarmin cytokine IL-33 in protective immune responses in a murine model of hookworm infection, which needs to be confirmed in human infection." (PMID 34662329, 2021). "In addition to IL-33, activation of lung ILC2s during hookworm infection requires LTC4 and its metabolite LTD4, which synergize with IL-33 signaling by activating NFAT." (PMID 38277692, 2024). "In the mouse hookworm infection model N. brasiliensis, TFF2 is required for induction of IL-33, early Type 2 cytokine responses, and contributes to clearance of worms from the gut." (PMID 34662329, 2021).
intestinal polyposis (4 papers, 2018 to 2023). "Accordingly, during intestinal polyposis IL-33 deficiency affects MC accumulation as well as the release of MC-derived proteases and cytokines." (PMID 37730723, 2023). "Regarding the role of IL-33 in colorectal adenomas, IL-33 signaling has been reported to promote intestinal polyposis via activation of the tumor stroma." (PMID 36466926, 2022). "Mechanistically, IL-33 activated tumor stroma to promote intestinal polyposis." (PMID 29568370, 2018).
intracerebral hemorrhage (4 papers, 2018 to 2025). A cerebrovascular disorder characterized by bleeding into one or both cerebral hemispheres including the basal ganglia and the cerebral cortex. "Moreover, the IL-31/IL-33 axis might have a role in intracerebral hemorrhage." (PMID 41155460, 2025). "The significance of serum IL-33 levels on the prognosis of patients with intracerebral hemorrhage (ICH) has not been well studied." (PMID 33854693, 2021).
keratitis (4 papers, 2013 to 2026). A corneal disease that is characterized by inflammation of the cornea. "For example, IL-33-stimulated M2 macrophages play a critical role in the recruitment of leukocytes by producing chemokines, whereas IL-33-polarized M2 macrophages significantly decreased keratitis caused by Pseudomonas aeruginosa." (PMID 23653627, 2013). "Collectively, it is of great importance to further investigate the double-edge functions and regulatory mechanisms of IL-33/ST2 in different types of keratitis and explore clinical strategies based on diverse infectious pathogens and immune responses." (PMID 32908451, 2020). "In this regard, the primary explorations of the corneal localization and functional roles of ST2 and IL-33 were separately reported using P. aeruginosa keratitis mice models." (PMID 32908451, 2020). "Therefore, it is suggested that IL-33 stimulation resulted in less disease severity and reduced cornea inflammation." (PMID 32908451, 2020).
memory impairment (4 papers, 2017 to 2025). "Overall, these findings provide insights into the potential therapeutic implications of IL-33 in addressing aging-induced bone loss and memory impairment." (PMID 39224568, 2024). "Noteworthily, RNS-induced neurobehavioral deficits, bodyweight loss, and spatial learning and memory impairment, as well as cell apoptosis, were reversed by IL-33 pretreatment." (PMID 32982679, 2020). "IL-33 may ameliorate D-gal–induced aging bone loss and memory impairment in mice by regulating IL-17, Tregs, BACE1 expression, and tau phosphorylation, thereby inhibiting inflammaging." (PMID 39224568, 2024). "However, the involvement of IL-33 in aging-mediated bone loss and memory impairment remains unclear and needs further investigation." (PMID 39224568, 2024). "However, the role of the IL-33 cytokine in the pathogenesis of aging-related bone loss and its impact on memory impairment remains unclear." (PMID 39224568, 2024). "This was corroborated in the 5xFAD mouse model of familial AD where CBD treatment ameliorated memory impairment through the regulation of IL33 and TREM2." (PMID 40811673, 2025). "In light of these evidences, rationally it can be proposed that IL-33 attenuates memory impairment through its intrinsic property to inhibit BACE-1 expression and tau phosphorylation." (PMID 39224568, 2024). "Thus,Il33−/− mice began to developcognition/memory impairments after 60–80 weeks." (PMID 28675392, 2017). "Mice lacking Il33 gene(Il33−/−) developed AD-likedisease after 60–80 weeks, which was characterized by tau abnormality and aheavy loss of neurons/neurites in the cerebral cortex and hippocampus accompaniedwith cognition/memory impairment." (PMID 28675392, 2017).
myocardial ischemia (4 papers, 2015 to 2022). A disorder of cardiac function caused by insufficient blood flow to the muscle tissue of the heart. "Interleukin-33 (IL-33) plays a protective role in myocardial ischemia and reperfusion (I/R) injury, but the underlying mechanism was not fully elucidated." (PMID 26571038, 2015).
polyp (4 papers, 2016 to 2023). A usually exophytic mass attached to the underlying tissue by a broad base or a thin stalk. "Although some studies evaluate IL-33 in serum from CRSwNP subjects, there are few studies regarding IL-33 in polyp tissue, and the results are inconsistent." (PMID 38137606, 2023). "TH2 cytokine expression was determined by means of flow cytometry in polyp explants cultured in the presence of recombinant human IL-25 or IL-33 to evaluate whether IL-17RB and ST2 expressed on polyp T cells were functional." (PMID 26684290, 2016). "Interestingly, similar to human tissue, the expression of IL-33 was significantly lower in the 3 months and 6 months mouse polyp model compared with the control mice." (PMID 27584662, 2016). "Contrastingly, a high level of expression of IL-33 was present in tissue from patients with CRSwNP, CRSsNP and healthy subjects, and the authors have raised the possibility that IL-33 could interact with an ST2 cell population within the polyp-inflamed mucosa." (PMID 38137606, 2023).
renal cell carcinoma (4 papers, 2018 to 2023). "In renal cell carcinoma, IL-33 was shown to stimulate tumor cell proliferation and chemoresistance." (PMID 37056569, 2023). "Serum IL-33 levels were increased in renal cell carcinoma (RCC) patients compared to healthy volunteers." (PMID 30483263, 2018).
sensitization (4 papers, 2017 to 2022). "We have previously reported that allergic sensitization through tape stripped skin, which breaks the skin barrier of WT mice, induces EoE-like inflammation via the IL-33-basophil axis." (PMID 35759448, 2022). "IL-33 is a key driver of allergic sensitization in the lungs of newborns, and that IL-33 enhances the function of dendritic cells to induce Th2 cell polarization." (PMID 28490737, 2017).
toxoplasmosis (4 papers, 2020 to 2024). A parasitic disease contracted by the ingestion or fetal transmission of toxoplasma gondii. "Our aim was to analyze the associations between the serum levels of IL-33 and IL-1β in IUGR and toxoplasmosis during pregnancy." (PMID 39065188, 2024). "Nevertheless, the acute stage of toxoplasmosis is associated with the ability of T. gondii to infect and lyse epithelial and endothelial cells, but whether these events lead to the release of IL-33 or if this affects the innate response to Toxoplasma is unknown." (PMID 33929319, 2021). "For instance, in the brain and eye IL-33 controls immunopathology and is instrumental for disease resolution, while in an oral model of toxoplasmosis, the action of this cytokine is detrimental to murine survival." (PMID 32363166, 2020). "In summary, further studies are necessary to confirm whether chronic human toxoplasmosis might exacerbate DS in pregnant women and, to evaluate the potentiality of neuroserpin, IL-33, and IL-17 as biomarkers for DS in T. gondii infection focusing on pregnant women from different genetic backgrounds." (PMID 38835777, 2024). "IL-33 signaling through the ST2 receptor has been shown to play a dual role in inflammation and can therefore have different effects on toxoplasmosis depending on the tissue." (PMID 32363166, 2020). "More studies are needed to fully determine the complex role of IL-33/ST2 in different infected tissues and stages of toxoplasmosis." (PMID 32363166, 2020). "Furthermore, the mean concentration of IL-33 was elevated in the toxoplasmosis+/IUGR+ group at 252.62 pg/mL, while it was 486.93 pg/mL in the toxoplasmosis-/IUGR group." (PMID 39065188, 2024).
triple-negative breast carcinoma (4 papers, 2019 to 2025). An invasive breast carcinoma which is negative for expression of estrogen receptor (ER), progesterone receptor (PR), and human epidermal growth factor receptor 2 (HER2). "The potential protective role of circulating interleukin-33 concentrations in triple-negative breast cancer risk requires further examination in future studies." (PMID 38301482, 2024). "In triple-negative breast cancer patients and in vivo mouse models, IL-33 engages eosinophil infiltration into tumors and is essential for the efficiency of cisplatin and anti-PD1 and anti-CTLA4 treatment." (PMID 37762328, 2023). "In triple-negative breast cancer, a high expression of IL-33 in tumor tissue was a predictor of the response to chemotherapy." (PMID 37762328, 2023). "Additionally, miR-455-5p promotes triple-negative breast cancer growth and immune evasion by targeting SOCS3, a negative regulator of cytokine signalling suggesting that microRNA-mediated modulation of ­cytokine pathways could influence responses to IL-33/ST2 and PD-1/PD-L1 co-inhibition." (PMID 41284319, 2025).
Ureteral obstruction (4 papers, 2021 to 2023). Obstruction of the flow of urine through the ureter. "Here we describe a novel role for nuclear IL-33 in regulating the fibroblast phenotype in murine kidney fibrosis driven by unilateral ureteral obstruction." (PMID 33420328, 2021). "Here, we combined analyses of unilateral ureteral obstruction in vivo with analyses of human fibroblasts in vitro to reveal a novel role for nuclear IL-33 as a repressor of interstitial cell extracellular matrix deposition." (PMID 33420328, 2021). "A nuclear localization of IL-33 was observed both in cells in the renal interstitial space that as a sequela to ureteral obstruction develop into α-SMA + myofibroblasts, and in primary human fibroblasts exposed to profibrotic stimuli." (PMID 33420328, 2021). "A likely explanation for this apparent discrepancy could be that the unrelenting pressure and subsequent tissue-damage induced by complete ureteral obstruction is strong enough to override the homeostatic mechanism exerted by IL-33." (PMID 33420328, 2021).
abdominal aortic aneurysm (3 papers, 2022 to 2025). Enlargement and ballooning of the vessel that supplies arterial blood to the abdomen, pelvis and legs. "We speculated that the inhibitory effect of A. muciniphila on the formation of abdominal aortic aneurysms might be related to the molecular immunity of distal IL-33 through gut microbiota, but it still needs further study." (PMID 35774450, 2022).
autoimmune hepatitis (3 papers, 2013 to 2018). Hepatitis caused by autoantibodies. "This study investigated the role of IL-33 in the pathogenesis of autoimmune hepatitis (AIH)." (PMID 30034292, 2018).
autoimmune thyroid disease (3 papers, 2021 to 2025). Inflammatory disease of the thyroid gland due to autoimmune responses leading to lymphocytic infiltration of the gland. "The effect of the IL-33/ST2 pathway on immune diseases is closely related to susceptibility to autoimmune thyroid disease and some genetic variants of IL-33/ST2 and its related neighboring genes, which provides new ideas for existing therapeutic approaches in the future." (PMID 39925809, 2025). "A recent study has shown that the IL-33/ST2 pathway is involved in the pathogenesis of autoimmune thyroid diseases." (PMID 39925809, 2025).
benign breast diseases (3 papers, 2014 to 2018). "Using Luminex and immunohistochemistry methods, we found that serum levels of IL-33 were nearly twofold higher in patients with BC, compared to patients with benign breast diseases." (PMID 24778632, 2014).
Brain tumor (3 papers, 2020 to 2025). "Brain tumor sections were subjected to immunohistochemistry with murine-specific IL-33 antibodies to detect host-derived IL-33." (PMID 39931535, 2025). "Herein, we reinforce a role for IL-33 as a major regulator of the brain tumor environment and provide mechanistic insight into how this environment promotes tumorigenesis." (PMID 33020472, 2020). "Notably, IL-33 prevents temozolomide (TMZ)-induced brain tumor apoptosis, and blocking IL-33/ST2 signaling can increase the sensitivity of tumors to TMZ." (PMID 34079543, 2021).
bronchiectasis (3 papers, 2016 to 2023). Segmental, irreversible dilation of the bronchial tree resulting in the accumulation of secretions which leads to obstruction. "Of the remaining variants only two were located within genes functionally related to the phenotype under study; these were periaxin (PRX) for the peripheral neuropathy and Interleukin-33 (IL33) for the bronchiectasis." (PMID 26059842, 2016). "In recent years, novel biomarkers, such as those related to IL-5, IL-33 and COL4A3 are emerging, but their expressions and potential roles in bronchiectasis still await investigation." (PMID 37653511, 2023).
chronic hepatitis C (3 papers, 2012 to 2016). "This study examined the potential role of IL-33 in the pathogenic process of chronic hepatitis C (CHC) in Chinese patients." (PMID 22315510, 2012). "In the present study, we measured serum IL-33 levels in a group of patients affected with chronic hepatitis C (CHC) at enrolment and after a course of pegylated (PEG)-IFN plus ribavirin." (PMID 23423835, 2012). "In the current study, we examined the concentrations of serum IL-33 and sST2 in patients with chronic hepatitis C (CHC), individuals with spontaneously resolved HCV infection (SR-HCV), and healthy controls (HC) to evaluate the potential role of IL-33/ST2 axis in the pathogenic process of CHC." (PMID 22315510, 2012).
chronic lung disease (3 papers, 2019 to 2023). According to the definitions of the American and British Thoracic Societies, including pulmonary functional tests, X-rays, and CT scans for items such as fibrosis, bronchiectasis, bullae, emphysema, nodular or lymphomatous abnormalities. "Recent research of inflammation models like post-viral mice with chronic lung disease and in patients with chronic lung disease indicate that extracellular ATP may play a role in IL-33 expression." (PMID 31795299, 2019).
cryptococcosis (3 papers, 2016 to 2024). An acute or chronic, localized or disseminated infection by Cryptococcus neoformans. "Interestingly, IL-22 deficient animals also show reduced IL-33 production in the lungs, which may lead to decreased Th2 axis activation during cryptococcosis and a lower presence of allergic-type responses." (PMID 39635124, 2024). "Recently, the infection-dependent release of the alarmin IL-33 has been identified as one of the main initial events for establishment of a type 2 polarized immune response in murine cryptococcosis." (PMID 32117319, 2020).
demyelinating disease (3 papers, 2016 to 2025). A broad group of disorders that affect the myelin sheaths that cover the neurons. "Our study suggests that the neuro-reparative features of poly-IC and IL-33 will have clinical applications in the treatment of demyelinating disease." (PMID 27022724, 2016). "Our study suggests that poly-IC, acting either directly or indirectly through the synthesis of IL-33 may be a candidate molecule for use as a therapeutic agent in demyelinating disease." (PMID 27022724, 2016). "Also, administration of IL-33 reduced the severity of experimental allergic encephalitis (EAE) a mouse model of demyelinating disease which shares similarities with human multiple sclerosis." (PMID 27022724, 2016). "Our studies suggest that poly-IC and IL-33 play a role in myelin repair by enhancing expression of myelin genes and are therefore attractive therapeutic agents for use as remyelinating agents in human demyelinating disease." (PMID 27022724, 2016).
edema (3 papers, 2016 to 2024). An abnormal accumulation of fluid beneath the skin, or in one or more cavities of the body. "Although the lack of protection from IL-33-induced pulmonary edema in Rag1–/– mice argues against a central role for T cells in the acute vasculitic phase, Th2 cells may be critical for the development of the asthmatic and infiltrative phases, whereas ILC2s drive the vasculitic phase." (PMID 33974563, 2021).
Erythema (3 papers, 2016 to 2025). Redness of the skin, caused by hyperemia of the capillaries in the lower layers of the skin. "The total scores (thickness, scales and erythema) were similar in IL-33-/- and WT mice." (PMID 27317338, 2016).
esophagitis (3 papers, 2022 to 2025). An acute or chronic inflammatory disease affecting the esophageal wall. "The pro-inflammatory cytokine IFN-gamma has been linked to IL-33 expression in oesophagitis, and is also raised in IBD31." (PMID 35798804, 2022).
Fulminant hepatitis (3 papers, 2013 to 2018). Acute hepatitis complicated by acute liver failure with hepatic encephalopathy occurring less than 8 weeks after the onset of jaundice. "In parallel, the L2-MHV3 infection in mice induced fulminant hepatitis associated with up-regulated IL-33 expression as well as pro-inflammatory cytokine microenvironment in liver." (PMID 24058536, 2013). "In conclusion, the cytokine IL-33 is rapidly up-regulated during Poly(I:C) and MHV3-induced fulminant hepatitis in mice, suggesting that IL-33 may act as an alarmin." (PMID 24058536, 2013). "Therefore, we aimed to investigate the expression of IL-33 in murine fulminant hepatitis induced by a Toll like receptor (TLR3) viral mimetic, poly(I:C) or by pathogenic mouse hepatitis virus (L2-MHV3)." (PMID 24058536, 2013). "In the present study, we aimed to investigate the expression and cellular sources of IL-33 in a Poly(I:C)- and L2-MHV3-induced fulminant hepatitis in mice." (PMID 24058536, 2013). "Our data showed that IL-33 expression is up-regulated in liver sinusoidal and vascular endothelial cells and hepatocytes during L2-MHV3-induced fulminant hepatitis." (PMID 24058536, 2013). "The liver sinusoidal endothelial cells, vascular endothelial cells and hepatocytes represent potential sources of IL-33 in Poly(I:C) and murine L2-MHV3 induced fulminant hepatitis." (PMID 24058536, 2013). "In conclusion, the alarmin cytokine IL-33 was over-expressed during fulminant hepatitis in mice with LSEC, VEC and hepatocytes as potential sources of IL-33." (PMID 24058536, 2013).